TNF (tumor necrosis factor)
Diseases named in the same sentence as TNF in open-access papers (continued):
Sharing a sentence is not in itself a finding about the gene and the disease.
rheumatoid arthritis (continued). "This distributed inhibition is predicted to overcome compensatory pathway activation that limits anti-TNF and JAK inhibitor monotherapies, positioning these polyphenols as rational leads for next-generation, multi-target disease-modifying strategies in rheumatoid arthritis." (PMID 41543645, 2026). "Population‐based study revealed increased risks of basal cell carcinoma (22%) and squamous cell carcinoma (88%) in patients with rheumatoid arthritis not receiving biologic agents, with additional risks observed in those treated with TNF inhibitors." (PMID 41567565, 2026). "Our findings revealed that ArthritoMab-induced rheumatoid arthritis resulted in significantly elevated levels of the pro-inflammatory cytokines TNF-α in the blood but not MCP-1 in the joints." (PMID 40709173, 2025). "In addition, saffron was shown to improve levels of ESR, CRP, TNF-alpha, MDA, and TAC in patients with rheumatoid arthritis when given at a daily dosage of 100 mg." (PMID 40365184, 2025). "Notably, in T cells, IL-17A/F, TNF-α, and CXCL1/2 were upregulated in LKP-treated mice, with KEGG enrichment of IL-17 and TNF signaling pathways, consistent with findings in rheumatoid arthritis where IL-17-producing Th17 cells drive synovial inflammation." (PMID 41459160, 2025). "Unlike biologics used for rheumatoid arthritis (TNF antagonists) and psoriasis (IL-17, IL-23 antagonists), the current biologics for SLE, especially with renal involvement, have shown only modest clinical benefits." (PMID 40977724, 2025). "TNF-α upregulates RANKL expression on synovial fibroblasts and stromal cells, activating osteoclast differentiation and contributing to bone resorption, as observed in inflammatory conditions, for example, rheumatoid arthritis." (PMID 40671914, 2025). "But it may be interesting to comment that inflammatory markers (especially TNF-α, IL-8 and MCP-1) were also differentially increased in the synovial fluid of a patient with Brucella bursitis as compared to samples from rheumatoid arthritis or septic arthritis." (PMID 40557315, 2025). "Details regarding how inflammatory cytokines such as TNFα regulate osteoclastogenesis in rheumatoid arthritis have not yet been fully elucidated, however." (PMID 40688496, 2025). "Head-to-head comparative effectiveness studies of adults (aged ≥18 years) with IMIDs (including rheumatoid arthritis, inflammatory bowel disease, psoriasis or psoriatic arthritis, or spondyloarthropathy) treated with either JAK inhibitors or TNF antagonists were included." (PMID 40928778, 2025). "Biologic disease-modifying antirheumatic drugs (bDMARDs), particularly tumor necrosis factor-alpha (TNF-α) inhibitors, have revolutionized the treatment of various inflammatory rheumatological conditions, including rheumatoid arthritis and juvenile idiopathic arthritis." (PMID 40585695, 2025). "However, excessive TNF production can trigger a self-perpetuating cycle of inflammation, driving the pathophysiological processes seen in autoimmune disorders such as rheumatoid arthritis (RA) in which elevated levels of TNF in the synovium and serum correlate with disease activity and joint damage." (PMID 40453083, 2025). "Overactivation of the nuclear factor κB (NF-κB) pathway by the STK IκB kinase (IKK) leads to the excessive production of proinflammatory cytokines [e.g., tumor necrosis factor-α (TNF-α) and interleukin-1β (IL-1β)], exacerbating conditions such as rheumatoid arthritis." (PMID 40547482, 2025). "Downregulation of TNF and JAK-STAT results in clinical benefits, including reduced inflammation and cellular senescence, increase in healthy tissue homeostasis, and improved outcomes for myopathies, rheumatoid arthritis, liver diseases, and cancer." (PMID 40848270, 2025). "Sarilumab is prescribed for adults with moderate-to-severe rheumatoid arthritis who have not responded adequately to or cannot tolerate at least one csDMARD or TNF-alpha inhibitor." (PMID 40142915, 2025).
rheumatoid arthritis (continued). "The KEGG analysis indicated that the up-regulated DEGs were involved in the “IL-17 signaling pathway”, “TNF signaling pathway”, and “rheumatoid arthritis” pathways, while the down-regulated DEGs showed no significant enrichment in any pathway." (PMID 40724298, 2025). "The histopathological improvements in the AA rat model, paired with the reduction in inflammatory markers, such as TNF-α and IL-6, suggest that BDE is effective in mitigating rheumatoid arthritis pathology through its anti-inflammatory and immunomodulatory effects." (PMID 40332334, 2025). "The approval of the first anti-tumor necrosis factor (TNF) monoclonal antibody, infliximab (IFX, Remicade®, Janssen; US in 1998, EU in 1999) radically changed treatment strategies for rheumatoid arthritis and for other chronic immune and inflammatory disorders." (PMID 40181987, 2025). "In rheumatoid arthritis patients, reduced parasympathetic tone, as measured by HRV, was correlated with higher levels of inflammatory cytokines like tumor necrosis factor-alpha (TNF-α) and interleukin-6 (IL-6)." (PMID 40700127, 2025). "Abatacept is prescribed for individuals with active, moderate-to-severe rheumatoid arthritis who have not responded adequately to previous treatment with disease-modifying antirheumatic drugs or TNF-α inhibitors." (PMID 40142915, 2025). "Studies found that participants with rheumatoid arthritis who experience a higher burden of CVD due to hypertension benefited from supplementation with a natural anti-inflammatory compound that reduced CRP, IL6, and TNFα." (PMID 39558500, 2024). "Anti-inflammatory biological agents, including but not limited to TNF-α inhibitors (e.g., Adalimumab and Etanercept), IL-1 inhibitors (e.g., canakinumab), and IL-6 inhibitors (e.g., Tocilizumab), have been used for the treatment of rheumatoid arthritis (RA) and other inflammatory diseases." (PMID 38722915, 2024). "Piper longum, a medicinal plant from the Piperaceae family, contains major compounds like piperlongumine, an alkaloid, which reduces inflammatory markers such as TNF-α, IL-6, and IL-23, while also inhibiting ROS production and the JNK/NF-kB signaling pathways in rheumatoid arthritis models." (PMID 39866300, 2024). "In patients with rheumatoid arthritis, dietary supplementation with n-3 PUFA results in significantly decreased IL-1β levels in plasma, and in healthy volunteers, diets enriched in fish oil n-3 PUFA lead to reduced TNF-α and IL-1β levels." (PMID 38892051, 2024). "Animal models commonly used to study human rheumatoid arthritis include collagen-induced arthritis (CIA), adjuvant-induced arthritis (AIA), human TNF transgenic mice, streptococcal cell wall-induced arthritis, proteoglycan-induced arthritis, and serum transfer-induced models." (PMID 39061843, 2024). "A previous in vitro study on patients with rheumatoid arthritis observed that TNF blockade does not suppress the production of IL-17A and IL-22." (PMID 39409006, 2024). "Combining anti-tumor necrosis factor therapy with cIAP1/2 inhibitors by blocking the BIRC2/BIRC3-mediated apoptotic pathway has the potential to improve therapeutic efficacy and effectively reduce symptoms and disease progression in rheumatoid arthritis." (PMID 39301019, 2024). "For example, stigmasterol treatment reduced TNF-α, IL-6, IL-1β, iNOS and COX-2 in collagen-induced rheumatoid arthritis (RA) rats, and increased the expression of anti-inflammatory cytokines (IL-10) by down-regulating NF-kB p65 and p38 MAPK expression in the joints." (PMID 38579176, 2024). "While osteoarthritis is not typically classified as an inflammatory arthritis like rheumatoid arthritis, inflammatory cytokines such as IL-1β, IL-6, and TNFα play a role in its pathogenesis." (PMID 39769285, 2024). "Tumor necrosis factor-alpha (TNF-α) plays a pivotal role in the inflammatory response and is a key cytokine involved in the pathogenesis of various inflammatory diseases, including rheumatoid arthritis." (PMID 39729480, 2024).
rheumatoid arthritis (continued). "Moreover, high levels of inflammatory/arthrogenic factors, including cytokines (TNF-α, IL-6, IL-7, IL-15, and BAFF) and chemokines (CCL-2, CCL-5, and CXCL-10) have been reported in the serum and/or synovia of rheumatoid arthritis patients." (PMID 38720890, 2024). "One study in subjects with rheumatoid arthritis was suggestive of less cardiovascular events with TNF-α blockade compared with non-biologic disease-modifying anti-rheumatic drugs, which was confirmed by a systematic review and meta-analysis." (PMID 39591217, 2024). "Activation of A2AR inhibits NF-κB signaling pathway and inflammatory cytokine (IL-1, IL-6, TNF, IFN) production, and increases the anti-inflammatory cytokine IL-10 release, which leads to autoimmune diseases such as rheumatoid arthritis, systemic lupus erythematosus, or type 1 diabetes." (PMID 38837964, 2024). "In vitro intervention cell assays of serum from rheumatoid arthritis patients demonstrated a negative correlation between IgG of galactose-free glycoforms and TNF-α production." (PMID 38576616, 2024). "Lee and collaborators (2017) have shown that treatment with IL-1β and TNF-α raised CCR7 expression in both precursors and differentiated osteoclasts, increasing their migratory activity toward CCL19 and CCL21 chemokines upregulated in rheumatoid arthritis." (PMID 36831188, 2023). "The C variant was reported to have a negative impact on response to anti-TNF treatment in Polish patients with rheumatoid arthritis." (PMID 37901227, 2023). "We also quantified CILP-M in two studies from patients with rheumatoid arthritis (RA), ankylosing spondylitis (AS) and osteoarthritis (OA) and explored the monitoring and prognostic potential of CILP-M in TNF-α inhibitory treatment and modified Stoke AS Spine Score (mSASSS) progression." (PMID 38066013, 2023). "Unfortunately, however, the authors did not receive any positive effects of 18βGA in the TNF-α triggered mouse model of rheumatoid arthritis." (PMID 36903944, 2023). "TNF-α, a 17-kDa protein produced by macrophages, lymphocytes, and natural killer cells, was identified as a key player in the inflammatory process, as elevated levels have been found in patients with inflammatory bowel disease (IBD) and rheumatoid arthritis." (PMID 37373082, 2023). "A study investigating rheumatoid arthritis found that memory Tregs (CD4+CD45RO+CD25+CD127low) can acquire the ability to produce pro-inflammatory cytokines, including not only IFN-γ and IL17, but also TNF, in response to inflammatory stimuli." (PMID 37047033, 2023). "Recombinant AREG upregulated the mRNA expression levels of vascular endothelial growth factor, IL-8, and IL-6, but not those of IL-1β or TNF-α in rheumatoid arthritis fibroblast-like synoviocytes." (PMID 37868614, 2023). "This is fully compatible with the patient having normal TNFα levels in serum prior to therapy initiation, an observation that has been made also in other TNFα-driven inflammatory diseases such as juvenile idiopathic arthritis (JIA) and rheumatoid arthritis (RA)." (PMID 37954595, 2023). "In contrast with the findings in healthy subjects, Salemi and colleagues observed an increase of Treg cells in patients with rheumatoid arthritis treated with TNF-alpha blockers after vaccination with a non-adjuvanted influenza vaccine." (PMID 36831046, 2023). "Antagonists to TNF-α have proven effective in inflammatory conditions such as Crohn’s disease and rheumatoid arthritis, but anti-TNF-α drugs have not shown benefits in patients with chronic heart disease." (PMID 37484982, 2023). "In addition, FTI decrease synovial TNF and IL-1 mRNA expression in rheumatoid arthritis (RA)." (PMID 38993912, 2023). "This has some parallels with therapies targeting TNF, which are effective in rheumatoid arthritis but not in multiple sclerosis, and indeed can worsen multiple sclerosis or provoke de novo central nervous system demyelination." (PMID 37563310, 2023).
rheumatoid arthritis (continued). "Among the four clusters of the neutrophils, C3 had DEGs that could be readily connected to functional pathways such as those involved in apoptosis, NFkB/TNF/IL17/TLR signaling and those that contribute to rheumatoid arthritis." (PMID 38149246, 2023). "The top eight enriched gene sets are: HIF-1 signaling pathway, TNF signaling pathway, AGE-RAGE signaling pathway in diabetic complications, NF-kappa B signaling pathway, ferroptosis, IL-17 signaling pathway, ovarian steroidogenesis, and rheumatoid arthritis." (PMID 37350944, 2023). "The tumor necrosis factor (TNF) is an important regulator of immune responses, and inhibition of TNF is reported in the treatment of many inflammatory diseases, including inflammatory bowel disease and rheumatoid arthritis in mouse models and patients." (PMID 36845140, 2023). "Patients with CTAP-EFM had statistically nonsignificant trends to be older, have longer-standing rheumatoid arthritis and be inadequate responders to TNF inhibitors." (PMID 37938773, 2023). "In 1999, a trial firstly proved the clinical benefit of adding etanercept, a tumor necrosis factor inhibitor (TNFi), to methotrexate in Rheumatoid Arthritis (RA) patients who did not respond to the standard of care." (PMID 35683344, 2022). "Unlike in human rheumatoid arthritis, citrullinated antigens are not specifically targeted by antibodies in murine TNF-induced arthritis, suggesting that these two PADs provide distinct contributions to immune cell function in inflammatory arthritis." (PMID 35083342, 2022). "TNF-α is an inflammatory cytokine that inhibits the differentiation of mesenchymal cells into osteoblasts and mediates the formation of osteoclasts, thereby inhibiting the process of bone formation and participating in the occurrence of inflammatory bone diseases such as rheumatoid arthritis (RA)." (PMID 36295902, 2022). "Furthermore, SZR72 inhibited the production of the inflammatory mediators TNF-α, calprotectin, S100A12, and HNP1-3 in blood cultures of rheumatoid arthritis patients." (PMID 35163002, 2022). "Anti-inflammatory biologic agents, including but not limited to TNF-α inhibitors (e.g., adalimumab), interleukin-1 (IL-1) inhibitors (e.g., canakinumab), and IL-6 inhibitors (e.g., tocilizumab), have been used in treating rheumatoid arthritis (RA) and other inflammatory diseases." (PMID 35887724, 2022). "TRMs from C15 and C29 were highly expressed the pro‐inflammatory cytokine, TNF‐α, that mediate tissue pathology in rheumatoid arthritis and IBD.[10b] We indeed observed significant enrichment of the TNF‐alpha signaling via nuclear factor‐κB (NF‐κB) pathway in these two groups." (PMID 35470584, 2022). "The level of LRG1 was also found to be correlated with CRP, erythrocyte sedimentation rate (ESR), and disease activity score 28 (DAS28), but not with the serum TNF-α levels in rheumatoid arthritis (RA)." (PMID 36569927, 2022). "Similarly, in both animal models and patients with rheumatoid arthritis or discogenic LBP, TNF-α blocking drugs were shown not only to reverse central pain responses but also to improve disability." (PMID 35492573, 2022). "This study examined the effect of tumor necrosis factor (TNF) inhibitors on weight gain in patients with seropositive rheumatoid arthritis compared with non-TNF therapy and disease activity." (PMID 35784983, 2022). "We found that the three groups of differential genes were indeed enriched in inflammatory pathways, which were all related to the rheumatoid arthritis pathway, and the pathway with differentially expressed genes induced by the antagonistic MLA was closely related to the TNF signaling pathway." (PMID 35323499, 2022). "Anti-TNF therapy has significantly improved disease control in rheumatoid arthritis, but a fraction of rheumatoid arthritis patients do not respond to anti-TNF therapy or lose response over time." (PMID 36009355, 2022).
rheumatoid arthritis (continued). "Studies examining the effects of the IL6 polymorphism in patients with rheumatoid arthritis, which has been linked to elevated Lp(a) levels, have shown that blocking the IL6 receptor, but not TNF-α signaling, decreased Lp(a) levels by 30–40%." (PMID 35621838, 2022). "Anti-TNF-α agents have demonstrated efficacy both in monotherapy and in combination with disease-modifying antirheumatic drugs (DMARDs) in the treatment of chronic immune-mediated inflammatory diseases, such as rheumatoid arthritis (RA), Crohn's disease (CD), PsO, and PsA." (PMID 34614113, 2021). "Cytokines TNF-α, IL-1β, IL-17, and transforming growth factor-β (TGF-β) levels were also significantly lowered after 10-days of treatment, and the effect was comparable with methotrexate, a drug used to treat rheumatoid arthritis." (PMID 33478498, 2021). "Swollen 28-joint count (SJC-28), Tender 28-joint count (TJC-28), CRP, erythrocyte sedimentation rate (ESR), uncarboxylated osteocalcin (UCOC), MMP-3, TNF, IL-6, and DAS28-ESR (Diseases Activities Score-28 for Rheumatoid Arthritis with ESR) levels are also decreased." (PMID 34770980, 2021). "Attempts to block TNF-α in SLE were not as successful as in rheumatoid arthritis and resulted in exacerbations of the disease as reviewed by De Bandt." (PMID 34768756, 2021). "The use of non-selective tumor necrosis factor (TNF) inhibitors is well known in the treatment of inflammatory diseases such as rheumatoid arthritis, Crohn's disease, and psoriasis." (PMID 33401396, 2021). "Notably, infant serum levels of the anti-TNFα mAbs infliximab and adalimumab may be equivalent to maternal levels following mAb treatment of rheumatoid arthritis (RA) during pregnancy." (PMID 33912195, 2021). "However, TNFα is elevated is a number of painful conditions in humans including chemotherapy-induced neuropathic pain (CIPN) and rheumatoid arthritis (RA)." (PMID 34938263, 2021). "For fenebrutinib, a Ph II study comparing fenebrutinib and adalimumab, a TNF-alpha inhibitor, in patients with rheumatoid arthritis had commonly reported non-serious adverse events of nausea, headache, anemia and upper respiratory tract infections." (PMID 34803999, 2021). "Electrical stimulation of the splenic plexus, in rats, has been shown to reduce levels of systemic tumor necrosis factor (TNF) after administration of the endotoxin lipopolysaccharide and mitigated clinical symptoms in a mouse model of rheumatoid arthritis." (PMID 32583891, 2021). "In January 2015, for better control of rheumatoid arthritis, methotrexate needed to be increased to 20 mg/week but without anti-TNF therapy because she had shingles one month earlier." (PMID 35610714, 2021). "Besides, RSV is also known to reduce TNF-α-induced IL-1β and MMP-3 production by suppressing PI3K-Akt signaling in fibroblastoid synoviocytes of rheumatoid arthritis." (PMID 34497510, 2021). "While anti-TNF treatment has proven success in several inflammatory diseases such as rheumatoid arthritis, it has not been directly investigated in CVD patients." (PMID 34300351, 2021). "Anti-TNF-α therapy using monoclonal antibodies that specifically bind to and neutralizes TNF-α has been studied for a long time and has led to significant advances in the treatment of rheumatoid arthritis." (PMID 34071276, 2021). "More specifically, it has been demonstrated that the biological action of IL-34 involved in inflammation is mediated through pro-inflammatory cytokines including tumor necrosis factor-alpha (TNF-α) and IL-1β in fibroblast-like synoviocytes (FLS) isolated from rheumatoid arthritis (RA) patients." (PMID 32409720, 2020). "The proinflammatory cytokines such as IL-1β, IL-6, TNF, CXCL9, CXCL10, and IFN-γ participate in the pathology of several chronic inflammatory diseases including rheumatoid arthritis, coronary diseases, cerebral malaria, tegumentary leishmaniasis, and Chagas diseases." (PMID 32385802, 2020).